CD22 (CD22 molecule)
Diseases named in the same sentence as CD22 in open-access papers (continued):
Sharing a sentence is not in itself a finding about the gene and the disease.
acute lymphoblastic leukemia (continued). "Near universal expression on B-cell acute lymphoblastic leukemia (ALL) blasts and the ability of rapid internalization has rendered CD22 an ideal target for ADC in B-ALL." (PMID 34441852, 2021). "CD19 and CD22 chimeric antigen receptor (CAR) T cell therapies have shown promising efficacy in relapsed or refractory B-lineage acute lymphoblastic leukemia (B-ALL)." (PMID 34642489, 2021). "Phase I and II trials that study the effect of CAR-T on B-cell maturation antigen (BCMA) or CD22 have shown potent antitumor activity for multiple myeloma (MM) and acute lymphoblastic leukemia (ALL), respectively." (PMID 34359816, 2021). "Salvage options for patients with relapsed B-cell acute lymphoblastic leukemia (B-ALL) include inotuzumab ozogamicin (InO), a recombinant, humanized anti-CD22 monoclonal antibody conjugated to the cytotoxic antibiotic calicheamicin." (PMID 33704192, 2020). "Furthermore, inotuzumab ozogamicin, an anti-CD22 antibody-drug conjugate, has been approved in the EU and US for the treatment of relapsed or refractory (R/R) B cell precursor acute lymphoblastic leukemia (BCP-ALL), providing another treatment option for these patients." (PMID 32856140, 2020). "The clinical activity and safety of single-agent InO compared with standard intensive chemotherapy in adults with relapsed or refractory (R/R) CD22+ B-cell acute lymphoblastic leukemia (ALL) was assessed in the phase 3 INO-VATE trial." (PMID 30859374, 2019). "The target CD22 is a B-acute lymphoblastic leukemia (B-ALL) specific antigen with restricted expression in the surface of full-grown B cells." (PMID 29642542, 2018). "In the majority of acute lymphoblastic leukemias (ALL) Siglec-2 (CD22) was identified as a useful target for cell-depletion therapy." (PMID 24592356, 2014). "Inotuzumab ozogamicin (InO), a CD22-directed antibody conjugated to calicheamicin, has demonstrated excellent efficacy in B-cell precursor (BCP) acute lymphoblastic leukemia (ALL)." (PMID 39648271, 2025). "Acute lymphoblastic leukemia (ALL) has been a major area of focus for multispecific antibody development due to the consistent expression of tumor-associated antigens such as CD19 and CD22 on B-lineage blasts." (PMID 40508128, 2025). "InO, a CD22-targeting ADC, has been explored in combination with various targeted therapies to develop tailored strategies for acute lymphoblastic leukemia (ALL) according to patient age and disease status." (PMID 41471096, 2025). "Inotuzumab ozogamicin (INO) is an anti-CD22 antibody-drug conjugate that was first evaluated in B-cell lymphomas but was subsequently shown to be highly effective in acute lymphoblastic leukemia (ALL)." (PMID 38734670, 2024). "CAR T cell functional assays were performed by coculturing CAR T cells with NALM6 acute lymphocytic leukemia tumor cell line that expressed CD19 and CD22 on the cell surface." (PMID 38864817, 2024). "CD22 and CD19 dual‐targeting chimeric antigen receptor T‐cell trials in patients with relapsed/refractory acute lymphoblastic leukemia." (PMID 37667978, 2023). "In acute lymphoblastic leukemia (ALL) and in CLL, Moxe showed a limited response rate, probably due to a lower CD22 expression." (PMID 36968995, 2023). "Despite the fact that BCMA- or CD22-targeted CAR T cells also exhibit tremendous anti-tumor activity in multiple myeloma and acute lymphoblastic leukemia, all these target antigens are highly restricted to the B cell lineage." (PMID 36389701, 2022). "As such, CD22 or tandem CD19 and CD22 targeting CAR-T cells are being pursued in treating B cell malignancies such as non-Hodgkin lymphomas and acute lymphoblastic leukemia." (PMID 34827170, 2021). "A recent study found that second generation of CARs derived from anti-CD22 mAb targeting a membrane proximal C-type Ig domain (m971) has superior antileukemic activity in B-cell acute lymphoblastic leukemia (BCP-ALL), compared with those targeting membrane distal Ig domains." (PMID 33333862, 2020).
acute lymphoblastic leukemia (continued). "Meanwhile, inotuzumab ozogamicin, a CD22 antibody conjugated to the same linker-drug moiety, demonstrated cytotoxicity against B cell lymphomas and was approved for treatment of acute lymphoblastic leukemia (ALL) in 2017." (PMID 31816964, 2019). "Recently, the use of chimeric antigen receptor (CAR) T-cell therapy, specific for CD22 was reported to provide high response rates for patients with B-cell acute lymphoblastic leukemia (B-ALL) who had failed chemotherapy and/or a CD19-targeted CAR T-cell treatment." (PMID 30323814, 2018). "CD22 is not only expressed on healthy or autoreactive B cells but also on the majority of B-cell lymphomas and on 65% of the acute lymphoblastic leukemia (ALL)." (PMID 30559744, 2018). "Shah' team developed new CAR-T cells targeting CD22, which showed encouraging results in B-cell precursor acute lymphoblastic leukemia, suggesting that CD22 CAR-T cells may be a joint or remedial therapy for CD19-negative ALL and CD19-negative relapses." (PMID 28413717, 2017). "Among these ADC candidates, Inotuzumab ozogamicin, an anti-CD22 calicheamicin conjugate developed by Pfizer, has started its Phase III study in treating relapsed and refractory acute lymphoblastic leukemia (ALL), and is expected to be launched in 2017." (PMID 28098746, 2017). "For instance, acute lymphoblastic leukaemia (ALL) expresses CD5, CD22 and CD45, while acute myeloid leukaemia (AML) expresses CD15, CD33." (PMID 21614238, 2006). "Commercially available is lnotuzumab ozogamicin (Besponsa), a calicheamicin immunoconjugate developed by Pfizer for the treatment of CD22-positive B-cell precursor acute lymphoblastic leukemia (B-ALL), which subsequently showed high efficiency against acute lymphoblastic leukemia (ALL)." (PMID 39770542, 2024). "These laboratory observations were then followed by several early phase clinical trials that showed significant efficacy of INO in acute lymphoblastic leukemia (ALL), ultimately prompting to its evaluation in a large, randomized trial in adults with relapsed/refractory CD22-positive B-cell ALL." (PMID 38734670, 2024). "SOC therapy for Acute Lymphoblastic Leukemia (ALL) is centered around consolidative chemoimmunotherapy combinations, which include Blinatumomab (an anti-CD20 monoclonal antibody) and Inotuzumab ozogamicin (an anti-CD22 antibody-drug conjugate)." (PMID 37920162, 2023). "Additionally, in an established acute lymphoblastic leukemia (ALL) xenograft mouse model, CD22-BiTE demonstrated tumor growth inhibition, comparable to blinatumomab." (PMID 37247022, 2023). "Inotuzumab ozogamicin (InO), a humanized anti-CD22 monoclonal antibody conjugated to the cytotoxic antibiotic agent calicheamicin, has demonstrated efficacy in the phase 3 INO-VATE study of adults with relapsed or refractory acute lymphoblastic leukemia (ALL)." (PMID 29330398, 2018). "CD22-targeted recombinant immunotoxins (rIT) are active in hairy cell leukemia or acute lymphoblastic leukemia (ALL), but not in mantle cell lymphoma (MCL) patients." (PMID 28423727, 2017). "Anti-CD22 antibody-drug conjugates (ADC) inotuzumab ozogamicin and moxetumomab pasudotox, were approved for B-cell acute lymphoblastic leukemia (ALL) and hairy cell leukemia, respectively." (PMID 38711850, 2024). "The underlying malignancies included T-acute lymphoblastic leukemia (ALL) (n = 1), diffuse large B cell lymphoma (DLBCL) (n = 4), and B-ALL (n = 3), and in accordance with it, CAR-T cells targeting CD7, CD19, and CD22 were infused, respectively." (PMID 39396970, 2024). "Inotuzumab Ozogamicin is a CD22-directed antibody conjugated to calicheamicin, approved in adults with relapsed or refractory (R/R) B cell acute lymphoblastic leukemia (BCP-ALL)." (PMID 35468945, 2022).
acute lymphoblastic leukemia (continued). "This includes CAR T cells directed against CD19 [for acute lymphoblastic leukemia (ALL), non-Hodgkin lymphoma (NHL), and chronic lymphocytic leukemia (CLL)]; CD22 (to treat ALL); and B cell maturation antigen (BCMA) to treat multiple myeloma." (PMID 33391257, 2020). "B cell acute lymphoblastic leukemia (ALL) and non-Hodgkin lymphoma (NHL) frequently express CD19, CD20 and CD22 on the cell surfaces." (PMID 31011424, 2019). "The B-cell lineage restricted receptor CD22, being overexpressed in the majority of B-cell non-Hodgkin lymphomas (B-NHL), as well as in B-cell precursor acute lymphoblastic leukemia (BCP-ALL), is a particularly attractive target for ADC approaches." (PMID 26605343, 2015). "Specific antitumor activity of the SPDP-based immunoconjugates with OARs of 1 : 1, 2 : 1, and 3 : 1 was tested on human Burkitt's lymphoma Daudi and pre-B acute lymphoblastic leukemia Nalm6 cells in comparison with CD22-negative human acute T-cell leukemia cell line Jurkat." (PMID 26605343, 2015). "Bone marrow aspiration confirmed the diagnosis of acute lymphoblastic leukemia (ALL) of French-American-British L2 type (90% blasts) and common ALL antigen (+) B ALL was seen with flow cytometry (CD10: 75%, CD19: 86%, CD22: 75%, TdT: 44%)." (PMID 25330528, 2014). "In Acute Lymphoblastic Leukemia (ALL), relevant targets include CD20 and CD22." (PMID 40486885, 2025). "Inotuzumab ozogamicin (INO), an anti-CD22 monoclonal antibody–drug conjugate (ADC), has been shown to improve remission rates and survival in patients with relapsed/refractory acute lymphoblastic leukemia (R/R ALL)." (PMID 40261550, 2025). "CD19 and CD22 are essential B-cell receptors involved in modulating B-cell receptor (BCR) signaling and are widely exploited as therapeutic targets in B-cell acute lymphoblastic leukemia (B-ALL)." (PMID 41465349, 2025). "One patient with B-cell acute lymphoblastic leukemia (B-ALL) has maintained minimal residual disease (MRD)-negative remission for over 14 months after CD19/CD22 bispecific CAR-T cell therapy." (PMID 34256851, 2021). "In addition, dual-targeted CAR T-cells (CD19/CD22, CD19/CD20) have shown promising activity in acute lymphoblastic leukemia (ALL), as well as B-cell malignancies." (PMID 34830980, 2021). "Combotox, a 1:1 combination of anti-CD19 and anti-CD22 immunotoxins, was conjugated to deglycosylated RTA, which showed higher efficacy than either IT in pediatric precursor B-lineage acute lymphoblastic leukemia (pre-B ALL)." (PMID 32182799, 2020). "Third, CD22 expression is present in 60–80% of B-cell lymphomas or leukemias, including hairy cell leukemia (HCL), chronic lymphoblastic leukemia (CLL), non-Hodgkin’s lymphoma (NHL), and acute lymphoblastic leukemia (ALL)." (PMID 28582973, 2017). "Inotuzumab ozogamicin (INO), an anti-CD22 antibody conjugated to a calicheamicin payload via a cleavable linker, received FDA approval for use as a single agent in patients with R/R B-cell precursor acute lymphoblastic leukemia (ALL), based on the phase III IN-NOVATE trial." (PMID 38966169, 2024). "Inotuzumab ozogamicin (InO) is a CD22-targeted ADC that has shown consistent efficacy and tolerability when combined with chemotherapy in CD22-positive B-cell precursor acute lymphoblastic leukemia (B-ALL), regardless of patient age, disease status, or treatment history." (PMID 41471096, 2025).
leukemia (98 papers, 2011 to 2026). A malignant (clonal) hematologic disorder, involving hematopoietic stem cells and characterized by the presence of primitive or atypical myeloid or lymphoid cells in the bone marrow and the blood. "CD22 exon 12 skipped isoform has been associated with more aggressive leukemias through the loss of CD22 immunoreceptor tyrosine-based inhibitory motifs." (PMID 40268897, 2025). "Active selection agents recognizing only one antigen on leukemia cells can cause antigen-loss relapse, which is a potential limitation of potent CD22-targeted immunotherapies." (PMID 35464476, 2022). "For CD22, therapeutic evasion is linked to down-modulation of the number CD22 proteins expressed on the extracellular aspect of the leukemia cell plasma membrane." (PMID 35222407, 2022). "This treatment effect could be addressed by using other antibodies (e.g., CD22) to identify cells of the B-lineage that may have leukaemia-associated genetic aberrations." (PMID 39851542, 2025). "Other pre-emptive approaches involve using antibody–drug conjugates that target residual leukaemia cells such as inotuzumab ozogamicin (an anti-CD22 antibody linked to calicheamicin) or moxetumomab pasudotox (an anti-CD22 antibody linked to a Pseudomonas exotoxin)." (PMID 34805054, 2021). "CD22ΔE12 is the first reported genetic defect implicating a B-cell co-receptor in a human lymphoid malignancy and linking homozygous mutations of the CD22 gene to a human disease and also the first genetic defect implicating intronic mutations in the pathogenesis of leukemia." (PMID 25599086, 2014). "Clinical interventions with CD22 CAR-T have effectively hindered leukemia cell proliferation in vivo." (PMID 40719826, 2025). "Eight patients experienced leukemia relapse: six (75.0%) with CD19+CD22+ relapse, one (12.5%) with CD19−CD22+ relapse, and one (12.5%) with CD19−CD22− relapse." (PMID 39754190, 2025). "Numerous pre-clinical and clinical studies have affirmed the anti-tumor efficacy of targeting CD22 in leukemia." (PMID 40719826, 2025). "Before treatment, the expression levels of CD19, CD20, and CD22 on the surface of leukemia cells were measured by flow cytometry in both groups (Rituximab group: CD19: 65.65%, CD20: 49.47%, CD22: 74.12%; Control group: CD19: 83.1%, CD20: 6.84%, CD22: 67.08%)." (PMID 38662336, 2024). "In this issue of the JCI, Aminov, Giricz, and colleagues revealed that leukemia cells resisting CD19-targeted therapy had reduced CD19 but also low CD22 expression and were sensitive to Bruton’s tyrosine kinase and/or MEK inhibition." (PMID 38618954, 2024). "The FDA has approved two antibody-drug conjugates targeting CD22 to deliver cytotoxic agents to B-cell lymphoma/leukemia cells." (PMID 36882399, 2023). "CD22 is expressed broadly on B-cell lymphomas and leukemias and is therefore a suitable alternative target to CD19." (PMID 37247022, 2023). "Overall, co-incubation with CAR-T decreases CD22 and CD19 surface antigen expression on leukemia cells surviving CD22 CAR-T co-culture." (PMID 35222407, 2022). "Combination therapies with mAbs have been developed for non-engineered cord blood NK cells in CRC with Cetuximab (anti-EGFR mAb, NCT05040568, row 24) and with PB-NK cells in pediatric leukemia with Epratuzumab (anti-CD22 mAb, NCT00941928, row 39)." (PMID 36348457, 2022). "The assay was carried out by culturing leukemia cells for 24 hours in the presence of 1 nM bryostatin for 24 hours, followed by the overnight addition of CD22-specific CAR-T for another 24 hour period, again in the presence of bryostatin." (PMID 35222407, 2022). "For the ALL lines NALM6 and REH, the killing of leukemia targets mediated by CD22 CAR-T was greatly enhanced by bryostatin." (PMID 35222407, 2022). "Recently, pharmacologic agents known to induce cellular differentiation or epigenetic modification of leukemia have been shown to impact CD22 and CD19 expression levels on B-ALL, and thereby increase sensitivity to CAR-T mediated cytolysis." (PMID 35222407, 2022).
leukemia (continued). "Inotuzumab ozogamicin is an antibody–drug conjugate (ADC) comprised of a human anti-CD22 antibody attached to calicheamicin that utilizes the CD22 epitope for the targeted delivery of toxic payloads to B-cell lymphoma/leukemia cells." (PMID 35418152, 2022). "The modulation of CD22 expression levels on the surface of leukemia cells is of great interest to the immunotherapy field." (PMID 35222407, 2022). "Using a range of effector (CD22 CAR-T) to target (leukemia line) ratios (E:T) we found that the co-incubation of CAR-T with leukemia cell lines induces a profound decrease in the number of cell surface antigens expressed on the cell surface." (PMID 35222407, 2022). "To further explore the relapse mechanism after sequential infusion of CAR-T cells, we examined the changes in CD19 and CD22 antigen expression on leukemia blasts by analyzing the MRD of three patient samples obtained at the pretreatment and relapse stages." (PMID 35317863, 2022). "VH-Fc 1-16-3 was conjugated with MMAE for a DDC study exploring killing of CD22 positive leukemia cells." (PMID 35464476, 2022). "The observation that relapsed disease is associated with a lower expression of CD22 antigen on the leukemia cell surface led us to explore the temporal interactions between CAR-T cells and leukemia cell line targets in the presence of bryostatin." (PMID 35222407, 2022). "Inotuzumab ozogamicin is an antibody directed against CD22 and conjugated with the cytotoxin calicheamicin whose use leads to uptake and killing of leukemia cells that highly express CD22." (PMID 34830969, 2021). "CD22, B-cell differentiation antigen of great significance, is expressed in most B-lineage lymphomas as well as leukemia cells." (PMID 34667217, 2021). "CD22 is highly expressed on B-cell lymphomas and leukemias so it has become an therapeutic target of cell therapy." (PMID 34256851, 2021). "Flow cytometric analysis revealed that patient 2 experienced relapse at 5 months after CD19/CD22 CAR T cell therapy with CD19-negative leukemia cells and low but variable CD22 surface expression on the leukemic blasts." (PMID 32245502, 2020). "DT2219 proved it has greater cytotoxicity against patient leukemia cells than monomeric LTTs made exclusively with anti-CD19 or anti-CD22 antibodies." (PMID 32630411, 2020). "The variables baseline leukemia blasts expressing CD22 in peripheral blood and percentage of blasts in peripheral blood were only tested in patients with ALL because this information was not collected in patients with NHL." (PMID 30859374, 2019). "The CD19-22 CAR was able to efficiently kill CD19+ and CD22+ human leukemia target cells in vitro, secrete IFN-γ in response to the target cells, and eradicate the leukemia in immune deficient mice." (PMID 30915277, 2019). "Searching for a molecule that enhances CD22-targeting rIT in vivo, we found the combination with paclitaxel to eradicate leukemia cells in 60% of KOPN-8-bearing mice which survive tumor-free for months." (PMID 28423727, 2017). "Expression of GFP-tagged full length and truncated CD22 proteins in transduced leukemia cells was further confirmed by fluorescence microscopy." (PMID 25599086, 2014). "To confirm the necessity of tethering SLP-76 to the membrane versus overexpression of cytosolic proximal signaling molecules in vivo, we compared MT-SLP-76 to overexpression of cytosolic SLP-76 or ZAP-70 in this model and found that only MT-SLP-76 restored functionality against CD22-low leukemia." (PMID 41131392, 2025). "Moreover, humanized anti-CD22 CAR-T cells have exhibited potent activity against leukemia cells even with low CD22 expression." (PMID 39582866, 2024). "However, a direct comparison of CD22-targeting CAR bearing a CD8α hinge or a CD28 hinge showed that CD8α exhibited more significant cytotoxicity against a decreased antigen density CD22 positive leukemia." (PMID 37444586, 2023).